MIR941-4 (microRNA 941-4)
Synonyms: hsa-mir-941-4; MIRN941-4
Gene: MicroRNA gene on chromosome 20 (63,919,756 to 63,919,827, forward strand). Ensembl gene ENSG00000216195.
Homologues: Paralogues in human: MIR941-2 (22% identical), MIR941-3 (0% identical), MIR941-5 (0% identical).